STAT3 (signal transducer and activator of transcription 3)
Diseases named in the same sentence as STAT3 in open-access papers (continued):
Sharing a sentence is not in itself a finding about the gene and the disease.
tumor (continued). "In tumor cells, activation of Stat3 involve in regulation of anti-apoptotic genes and cell cycle regulators, such as Bcl-xL, Bcl-2, Cyclin D1 and PCNA." (PMID 27563884, 2016). "We also show that suppressing IL-6 or inhibiting the STAT3 pathway significantly decreases CTC seeding in primary tumours." (PMID 26623559, 2016). "Stat3 regulates tumorigenesis and tumor inflammation and behaves in an oncogenic manner depending on the genetic background of the tumor." (PMID 27344175, 2016). "BALB/c nude mice were subcutaneously injected with the indicated number of Stat3-knockout or WT cells to evaluate tumour initiation 3 months later." (PMID 27553854, 2016). "We show that the environment created by ES cells has a suppressive effect on 4T1 cells by downregulation of Stat3 in these tumor cells." (PMID 27460364, 2016). "Apart from direct inhibition of tumor growth, blocking STAT3 activation is of potential value in combating chemoradiotherapeutic resistance of HNSCC." (PMID 26784960, 2016). "Our in vitro and in vivo results clearly demonstrated that the anti-tumor effects of CPA-7 are closely correlated with signal transducer and activator of transcription 3 (STAT3)." (PMID 27435207, 2016). "STAT-3 promotes tumor-cell survival and proliferation in tumor cells, as well as invasion and immunosuppression." (PMID 27413756, 2016). "It has been proposed that STAT3 activation in cancer cells is often mediated by cytokines and/or growth factors synthesized within the tumor microenvironment." (PMID 27102295, 2016). "STAT3 can induce an immunosuppressive tumor microenvironment with both direct and indirect effects on NK cells." (PMID 27148255, 2016). "Using this bioluminescence imaging system, we can simultaneously track the ES-CM on tumor growth (Fluc) and Stat3 signal pathway activation (Rluc) in vivo and in vitro." (PMID 27460364, 2016). "STAT-3 target genes are involved in several cellular events related to cancer metastasis, such as invasion, cell survival, angiogenesis and tumor-cell immune evasion." (PMID 27834913, 2016). "Several studies have identified Signal Transducer and Activator of Transcription 3 (STAT3) as an important molecule involved in tumor escape from immunosurveillance through the induction of several genes responsible for immunosuppression." (PMID 26910842, 2016). "Treatment of tumor-bearing WT mice with oxaliplatin was associated with emergence of a tumor-infiltrating CD19+CD138+IgA+ plasma cell population that expressed IL-10, PD-L1, phosphorylated Stat3, and Fas-L." (PMID 27437104, 2016). "In pancreatic ductal adenocarcinomas (PDACs), constitutive activation of STAT3 by phosphorylation of Tyr705 has been reported in 30% to 100% of human tumor specimens, as well as in many PDAC cell lines." (PMID 27577070, 2016). "Analysis of the tumor samples revealed that physalin A decreased Tyr705-p-STAT3 levels, and increased caspase-3 activation." (PMID 26843613, 2016). "STAT3, robustly activated by interleucin-6, is well studied for promoting tumor progression and poor prognosis." (PMID 27090655, 2016). "The binding of IL-6 to its receptor gp130 activates JAK2 which goes on to activate several downstream tumor promoters such as STAT3." (PMID 27756885, 2016). "Studies suggest that sorafenib also has a tumor suppression role in CCA in part through inhibition of STAT3 signaling pathway." (PMID 26956050, 2016). "BMP-2 induces EMT and promotes colon cancer cell migration and invasion by increasing STAT3-mediated tumor stemness." (PMID 27661009, 2016). "VEGFR2 was activated on IECs from patients with CAC, and VEGFR signaling via STAT3 was required for proliferation of IECs and tumor growth in mice." (PMID 26938566, 2016). "Although an in vitro study suggests that IL-6 suppresses in vitro growth of some cancer cells, IL-6/STAT3 has been shown to promote tumor progression and immune escape in a variety of in vivo models." (PMID 27006530, 2016).
tumor (continued). "We then investigated both STAT1 (tumour suppressor) and STAT3 (oncoprotein) activity in JAK/STAT pathway after gefitinib monotherapy." (PMID 26909593, 2016). "Activation of the JAK/STAT3 pathway enhances tumour progression, proliferation, invasion, immunosuppression, and therapy resistance." (PMID 26623559, 2016). "In normal cells, STAT3 activation is strictly controlled, but activated STAT3 has been detected in a variety of human tumor specimens and tumor cell lines, which suggests it plays a critical role in the occurrence and development of tumors." (PMID 27504822, 2016). "STAT3 is a transcription factor frequently activated in cancer cells via cytokine and growth factor signaling, with resultant tumor gene expression for survival, angiogenesis, and invasive/metastatic phenotypes." (PMID 27323862, 2016). "Our results indicate that Rhus coriaria extract (RCE) abolishes the migration, invasion of TNBCs, suppresses angiogenesis and reduces tumor growth in vivo via inhibition of STAT3, NFκB and nitric oxide (NO) pathways." (PMID 26888313, 2016). "Ectopic expression of GRIM-19 in human GC cells inhibited STAT3 activation and its downstream targets to induce cell cycle arrest and cell apoptosis in vitro and to suppress tumor formation in vivo." (PMID 27167343, 2016). "In contrast, the phospho-STAT3 (p-STAT3) level showed significant reduction in Mito-Ob mice, and further reduced in tumor bearing mice." (PMID 27005704, 2016). "At low doses, CPA-7 depletes the DNA binding capacity of STAT3 leading to down-regulation of genes down-stream of STAT3 and, ultimately, to tumor regression." (PMID 27435207, 2016). "MiR21 and miR181b-1 are important STAT3 effectors whose ablation in A549 cells results in decreased tumor growth." (PMID 27602766, 2016). "STAT3 can increase tumor cell proliferation, survival, and invasion, while suppressing anti-tumor immunity." (PMID 27821810, 2016). "Persistent activation of STAT3 is commonly observed in tumor tissues and it is the core transcription factor that links inflammation to cancer." (PMID 27383632, 2016). "A recent study has shown that STAT3 signaling controls the IL-12:IL-23 ratio in the tumor microenvironment." (PMID 27148255, 2016). "Signal transducer and activator of transcription-3 signaling has been shown to regulate the cytokine balance and functional interactions between NKs and other hematopoietic cells in the tumor microenvironment." (PMID 27148255, 2016). "In summary, we demonstrated evidence that EBI3 associated with IL-12p35, gp130, and p-STAT3 are highly expressed in CRC cells to inhibit antitumor CTL response and promote tumor growth in CRC." (PMID 27247488, 2016). "While STAT3 signaling in transformed epithelial cells promotes tumor growth by increasing response stimuli in pro-survival and cell cycle genes, STAT1 is known to suppress tumorigenesis through its function in regulating IFNγ." (PMID 27472371, 2016). "In fact, it has been shown very recently that due to the hypoxic conditions prevailing in the tumor microenvironment, MDSCs downregulate STAT3 activity mediated by CD45 tyrosine phosphatase upregulation." (PMID 27827921, 2016). "Despite this compelling evidence, only the effect of STAT3 in the tumor cells is studied, while immune cells have been largely disregarded." (PMID 27029037, 2016). "Intracranial drug availabilities, tumor sizes, average life spans and the impacts on STAT3 signaling, apoptosis and autophagy rates were evaluated." (PMID 27716625, 2016). "The ability of triterpenes is evidence to inhibit the inflammation in the tumor micron-environment associated with greater reduction of Cox-2 and Twist1 proteins more inhibition of activation of IGF-1R, Stat3, and Src." (PMID 27378920, 2016). "And STAT3 takes intrinsic activator effects in cancer inflammation and in the regulation of the tumor microenvironment." (PMID 27274723, 2016).
tumor (continued). "A connection between S1P and STAT3 activation has also been shown to be critical for tumor progression." (PMID 27800303, 2016). "We also showed that targeting STAT3 using specific inhibitor, S3I-201, killed TICs in suspension culture and inhibited tumour initiation." (PMID 27306323, 2016). "Further mechanistic analysis revealed that secretion of lymphotoxin (LT) by infiltrating B cells stimulates LTβR on CaP cells to induce nuclear translocation of IKKα and activation of STAT3, thereby driving androgen-independent tumor growth after castration." (PMID 27437104, 2016). "Since Janus kinases (JAKs) mediate STAT3 activation in tumor angiogenesis, we first tested the effect of VEGFA on Jak1 and Jak2 tyrosine phosphorylation in HRMVECs." (PMID 27210483, 2016). "The relationship between total and ph-STAT3 tumour cell expression and CSS using Kaplan-Meier log rank test was subsequently examined." (PMID 27769057, 2016). "We collected tissue at 3 and 7 days after transgene activation to examine cytokine/Stat3 and mTOR/S6 signaling during tumor initiation and early expansion." (PMID 26859571, 2016). "Then, western blot analysis was used to assess the expression of P-Stat3, Stat3, and ER stress-associated protein ATF4 in MDSCs obtained from the spleens of tumor-bearing mice." (PMID 27655678, 2016). "STAT3, a key pathway mediating immunosuppression in the tumor microenvironment, is identified as the target of miR-124 in the regulation of T-cell functions." (PMID 27757114, 2016). "Sal further reduced the expressions of STAT3-modulated Bcl-2 and Bcl-xL both at mRNA and protein levels, and increased the levels of pro-caspase-3 all known to promote tumor survival and tumor growth." (PMID 27058891, 2016). "In our study, CPA-7 treatment reduced the phosphorylation of STAT3 resulting in a significant retardation of tumor progression, which underscores the pivotal role of STAT3 in PC treatment." (PMID 27435207, 2016). "Below, we discuss the impact of STAT3 signaling on NK activation and function in the tumor microenvironment." (PMID 27148255, 2016). "STAT3 also is a key mediator of oncogene addiction and supports the self-renewal of tumor-initiating cancer stem cells that contribute to cancer initiation, cancer maintenance, and relapse in several types of tumors." (PMID 27027445, 2016). "Our data show that tumor-released soluble factors are sufficient to induce STAT3 activation, leading to increased expression of IL-4Rα in monocytes." (PMID 27317770, 2016). "Although both mCLCA5 and pStat3 are expressed predominantly at the invasive edge of the tumour, minimal co-localization of nuclear Stat3 and cytoplasmic mCLCA5 is observed." (PMID 27711075, 2016). "STAT3 drives tumor cell survival and proliferation, epithelial-to-mesenchymal transition (EMT), metastasis, and resistance to chemotherapy and radiation." (PMID 27148255, 2016). "STAT3-targeted tumor cells were more resistant to lysis by purified primary NK cells in vitro, and the growth differences between STAT3-targeted and WT tumors in vivo were abrogated in mice lacking NK cells." (PMID 27148255, 2016). "IL-22 signaling directly activates STAT3 in epithelial cells and increases stemness and tumorigenic potential in tumor cells through the methyltransferase DOT1L." (PMID 27148488, 2016). "The gut microbiota has also been shown to enhance tumor burden in ApcMin/+ mice partially via STAT3 phosphorylation." (PMID 27121311, 2016). "Growing studies identified novel tumor-promoting functions of STAT3 in mitochondria metabolism, drug resistance, epigenetic regulation, cancer stem cells and pre-metastatic niches." (PMID 26959884, 2016). "A possible mechanism through which STAT3 is hyperactivated in tumors involves the autocrine production of IL-6 from tumor cells." (PMID 26888313, 2016).
tumor (continued). "The aim of the present study was to examine the relationship between tumour cell expression of total and phosphorylated STAT1 (ph-STAT1) and STAT3 (ph-STAT-3), components of tumour microenvironment and survival in patients with invasive ductal breast cancer." (PMID 27769057, 2016). "Mitochondrial STAT3 has been reported in a variety of cell types and tissues leading to a wide range of cellular outcomes including tumor growth, cell death/survival, and immune regulation." (PMID 27695477, 2016). "As S1 Fig shown, CCK-BR, p-STAT3 and p-Akt protein levels were decreased in the tumor tissues in the NCI-N87/miR-148a group." (PMID 27518872, 2016). "This meta-analysis is the most comprehensive assessment of the literatures regarding STAT3 expression and tumor prognosis to date." (PMID 26959884, 2016). "The IHC staining of total and ph-STAT1 and STAT3 was homogenous in both the cytoplasm and nuclei of tumour cells, which is consistent with previous reports." (PMID 27769057, 2016). "Instead, infiltration of inflammatory cells during tumor expansion likely creates a cytokine-rich microenvironment leading to STAT3 activation in responsive cell populations." (PMID 26859571, 2016). "In summary, IL10 triggers positive feedback between JAK1 and Src to amplify the activity of STAT3, thus leading to tumor formation." (PMID 26956044, 2016). "Due to the strong association observed between both ph-STAT1 and ph-STAT3 and tumour necrosis, the relationship between ph-STAT1 and ph-STAT3 tumour cell expression with CSS in patients with high tumour necrosis was subsequently examined." (PMID 27769057, 2016). "Collectively, our results demonstrate for the first time that the IL-6/STAT3 signaling axis is a key element of tumor-stromal interaction between PSCs and tumor cells, playing a critical role in the progression from pre-neoplastic PanINs to PDAC." (PMID 27602757, 2016). "mda-9 also regulated STAT3 expression, which is a key contributor to cellular transformation and tumor maintenance in many cancer contexts, including GBM." (PMID 27472461, 2016). "In some cases, IL-10 improves the metastatic capability of lung tumor cells by increasing the vascular density in the primary tumor and increasing the resistance of lung tumor cells to apoptosis by activating STAT3 pathway." (PMID 27445423, 2016). "Given the hyperplastic phenotype in the Myc Stat3 CKO mice, we investigated if loss of Stat3 in MMTV-Myc mice accelerated tumor formation." (PMID 27589562, 2016). "Previous studies have shown the anti-tumor effect of PZH by suppressing STAT3 activation and regulating the Bcl-2 family in colon cancer." (PMID 27338343, 2016). "STAT3 removal resulted in a reduction of PMN-MDSCs in the tumor and an increased effector T cell/Treg ratio." (PMID 27029037, 2016). "The anti-tumor action of the FXR ligand was associated with the inhibition of several leptin-induced pathways, such as JAK2/STAT3, AKT and MAPK." (PMID 26899873, 2016). "This CTLA-4 aptamer-based targeting delivery of STAT-3 siRNA to T lymphocytes resulted in inhibition of tumor growth and of metastasis." (PMID 27413756, 2016). "Altering these conditions through aberrant STAT3 activation can establish an immunosuppressive circuit between tumor cells and infiltrating macrophages, DCs and NK cells, driven by STAT3 activation in all three subpopulations." (PMID 27148255, 2016). "In some circumstances, STAT3 is regarded as an oncogene, while in others its tumor suppressing and prognosis ameliorating effects have also been identified." (PMID 27577070, 2016). "RT–PCR and immunoblot analysis confirmed that the expression level of miR-125a, STAT3, p-STAT3 (Tyr705), Bcl-2 and Bcl-xL in HeLa/PR cells from the representative tumor mass." (PMID 26878391, 2016). "On the other hand, IL-17 increases the level of IL-6 and IL-8 in NSCLC cell lines and activates the STAT3 signaling pathway, mediating tumor angiogenesis." (PMID 27445423, 2016).
tumor (continued). "Perhaps more importantly, STAT3 activation in tumor cells triggers a cascade of cytokine and growth factor production that reprograms the tumor microenvironment, skewing it toward immunosuppression." (PMID 27148255, 2016). "We specifically discovered that the ES cell microenvironment sufficiently suppressed Stat3 signaling pathway activation in aggressive tumor cells, leading to a reduction in tumorigenesis and invasiveness." (PMID 27460364, 2016). "Inhibition of the STAT3 pathway often sensitizes radio-resistant tumor cells in various cancers to irradiation." (PMID 26755645, 2016). "Persistent activation of STAT3, in diverse human cancers, increases tumor cell proliferation, survival, angiogenesis and metastasis." (PMID 27690342, 2016). "Supernatants from STAT3-targeted tumor cells increased the expression of NK activation markers, such as CD69, NKG2D, Fas ligand, granzyme B, perforin, and IFN-γ." (PMID 27148255, 2016). "This is explained by the fact that many of the triggers that activate STAT3 are abundantly present in the tumor microenvironment (TME)." (PMID 27029037, 2016). "Enhanced S1PR1 upregulated the expression of IL-6, a pro-inflammatory cytokine crucial for STAT3 activation, inflammatory cell-mediated transformation, and tumor progression." (PMID 27129720, 2016). "Pharmacodynamic analysis showed that phosphorylation of STAT3 in the Ruxolitinib-treated tumor tissues was significantly suppressed." (PMID 26701727, 2016). "The immunomodulating property is represented by the constitutive activation of STAT3 signaling as tumor promoting inflammatory mechanism." (PMID 27349385, 2016). "Persistent activation of STAT3 is involved in promoting tumor cell proliferation, survival, tumor invasion, angiogenesis and immunosuppression, inducing and maintaining a pro-carcinogenic inflammatory microenvironment." (PMID 26959884, 2016). "Given the pivotal role in tumor development, STAT3 represents an attractive therapeutic target for solid tumors." (PMID 26959884, 2016). "Activation of the STAT3 signaling pathway participates in M2 polarization, which promotes tumor progression." (PMID 27172798, 2016). "Inhibition of IFN-α-stimulated STAT3 activation by emodin is consistent with previous observations that emodin inhibits Jak2 to suppress activation of STAT3 in tumor cells." (PMID 26683360, 2016). "This important finding defines a novel mechanism of PSC secreted IL-6 mediated activation of STAT3 signaling, as a critical regulator of tumor initiation and progression of PDAC." (PMID 27602757, 2016). "There is dual hope in these STAT3-directed therapies; on the one side, they are expected to block STAT3-mediated growth promoting and pro-survival signals in the tumor cells themselves." (PMID 28149296, 2016). "Infiltrating TAMs also enhanced tumor-initiating properties of CD44+ALDH1+ pancreatic CSCs by activating STAT3 signaling." (PMID 26980947, 2016). "Activated STAT3 in tumor cells impacts anticancer immunity as well, due to its ability to regulate cytokine and chemokine expression by the tumor as well as the expression of growth factors and surface markers on infiltrating immune cells." (PMID 27148255, 2016). "Persistent activation of STAT3 signaling is involved in promoting tumor cell proliferation, metastasis, invasion, angiogenesis and immunosuppression." (PMID 27835881, 2016). "Experiments herein demonstrated that hGH or hPRL act as tumor produced autocrine or paracrine growth factors that promote the activation of STAT3." (PMID 27102295, 2016). "To examine the involvement of STAT3 activity in macrophage AEG-1-mediated MMP-9 up-regulation in tumor cells, we inhibited STAT3 activation in FaDu cells with AG490, which is a pharmacological inhibitor of the upstream STAT3 activator janus kinase." (PMID 27793010, 2016). "The downstream transcription factors STAT3 and p65NFκB, both of which are tumor-promoting factors, were clearly phosphorylated and activated in the colons of Shp-2IEC-KO mice." (PMID 27582544, 2016).